RIPK3 (receptor interacting serine/threonine kinase 3)
Diseases named in the same sentence as RIPK3 in open-access papers (continued):
Sharing a sentence is not in itself a finding about the gene and the disease.
Hyperammonemia (1 paper, 2025). An increased concentration of ammonia in the blood. "In the present study, hyperammonemia was associated with increased hepatic expression of both RIPK1 and RIPK3." (PMID 40053595, 2025). "Inhibition of RIPK1 with its selective inhibitor RIPA-56 protected against hyperammonemia and restored RIPK3 protein expression levels and prevented liver cell death and fibrogenesis." (PMID 40053595, 2025). "On the basis of the finding that hyperammonemia induces increased expression of the necroptosis proteins RIPK1 and RIPK3, we aimed at assessing whether inhibition of this pathway would protect against hyperammonemia-induced liver injury and further hyperammonemia." (PMID 40053595, 2025). "This suggests that RIPK3-dependent necroptosis, as opposed to caspase-8–dependent apoptosis, may be the primary form of cell death induced by hyperammonemia." (PMID 40053595, 2025).
Hyperbilirubinemia (1 paper, 2023). An increased amount of bilirubin in the blood. "Further, hyperbilirubinemia in patients was associated with higher RIPK3 expression in hepatocytes." (PMID 37072399, 2023).
Hypertension (1 paper, 2025). The presence of chronic increased pressure in the systemic arterial system. "RIPK3 levels showed an association with hypertension (p = 0.025)." (PMID 41009652, 2025).
hyperthyroidism (1 paper, 2023). Overactivity of the thyroid gland resulting in overproduction of thyroid hormone and increased metabolic rate. "Our findings reveal that GD hyperthyroidism aggravates cognitive deficits in AD mice and induces Aβ deposition and neuronal loss by inducing neuroinflammation and RIPK3/MLKL-mediated necroptosis." (PMID 37740205, 2023). "In conclusion, our findings suggest that GD hyperthyroidism aggravates cognitive deficits and Aβ deposition in mice by inducing neuroinfammation and RIPK3/MLKL-mediated necroptosis in the brain." (PMID 37740205, 2023).
hypertrophic cardiomyopathy (1 paper, 2022). A condition in which the myocardium is hypertrophied without an obvious cause. "New targeted drugs for RIPK3 inhibition for clinical targeted therapy of hypertrophic cardiomyopathy could significantly improve clinical outlook for the disease." (PMID 36046685, 2022). "The present study is aimed at investigating how the RIPK3 inhibitor GSK'872 regulates CaMKII activity and exploring its effect on hypertrophic cardiomyopathy (HCM)." (PMID 36046685, 2022).
Impaired glucose tolerance (1 paper, 2016). An abnormal resistance to glucose, i.e., a reduction in the ability to maintain glucose levels in the blood stream within normal limits following oral or intravenous administration of glucose. "Therefore, to evaluate whether one of these tissues contributes to the impaired glucose tolerance in Ripk3-deficient mice, we measured serum insulin levels and performed insulin tolerance tests (ITTs) in WT and KO mice fed with NCD or CD-HFD." (PMID 27323669, 2016).
intestinal polyp (1 paper, 2021). Discrete abnormal tissue masses that protrude into the lumen of the intestine. "After IL-6R antibody treatment for 10 weeks, the anti-IL6-R-treated Apcmin/+Ripk3-/- mice showed fewer intestinal polyps than UT Apcmin/+Ripk3-/- mice." (PMID 33996591, 2021).
Krabbe disease (1 paper, 2021). A lysosomal disorder that affects the white matter of the central and peripheral nervous systems. "Findings by Vitner and colleagues suggested that Rip1 and Ripk3 expression was selectively increased in Gaucher and Krabbe disease brain, and did not report such changes in experimental models of other sphingolipidoses, such as Niemann-Pick C or the GM2 gangliosidosis SD." (PMID 34172992, 2021).
leukocytosis (1 paper, 2014). "Caspase-8 heterozygosity or Bid deletion did not prevent the leukocytosis, whereas Ripk3 and Mlkl deletion markedly reduced it, suggesting the hematopoietic phenotype is driven predominantly by necroptosis." (PMID 25443632, 2014).
lymphoproliferative syndrome (1 paper, 2019). A disorder characterized by proliferation of lymphocytes at various stages of differentiation. "When aged, Ripk3−/−Fadd−/−Ripk1K376R/K376R and Mlkl−/−Fadd−/−Ripk1K376R/K376R mice developed lymphoproliferative syndrome with an accumulation of CD3+B220+ lymphocytes in peripheral lymphoid organs seen in Ripk3−/−Fadd−/− and Mlkl−/−Fadd−/− mice 19–22,41–43." (PMID 31519886, 2019).
memory impairment (1 paper, 2023). "Thus, RIPK3 inhibition is capable to recover aged mice from learning and memory impairment." (PMID 36973898, 2023).
metastatic cancer (1 paper, 2022). A carcinoma which has spread from the original site of growth to another anatomic site. "In addition, RIPK3 expression also induced natural killer (NK) T-cells-mediated immune response via the activation of mitochondrial PGAMF-NFAT/Drp1 signaling, independent of the necroptosis pathway, and that anti-tumor response of NK T-cells to metastatic cancer cells is diminished in RIPK3−/− mice." (PMID 36361505, 2022).
myelodysplastic syndrome (1 paper, 2022). A clonal hematopoietic disorder characterized by dysplasia and ineffective hematopoiesis in one or more of the hematopoietic cell lines. "Ripk3/Mlkl-mediated necroptosis is detected in bone marrow (BM) samples from patients with aplastic anemia (AA) and myelodysplastic syndromes (MDS)." (PMID 35561683, 2022).
Myocardial necrosis (1 paper, 2022). Irreversible damage to heart tissue (myocardium) due to lack of oxygen after a heart attack (myocardial infarction). "In addition, the same group observed that RIPK3-deficient (Ripk3−/−) murine hearts became more resistant to I/R-induced myocardial necrosis comparative to WT counterparts." (PMID 35958271, 2022).
myomatous neoplasm (1 paper, 2020). A benign or malignant mesenchymal neoplasm arising from smooth, skeletal, or cardiac muscle. "RIPK3, TFAP2E and TMEM214 were good candidates for the non-neural crest tumors since they are mutated in sarcomas (TCGA SARC), myomatous neoplasms and in hepatocarcinomas (TCGA LIHC) at the somatic level." (PMID 33112832, 2020).
nasopharyngeal carcinoma (1 paper, 2024). A carcinoma arising from the nasopharyngeal epithelium. "Shikonin functions mainly through RIPK1 in the PANC-1 cell line and has no obvious effect on RIPK3; however, in AsPC-1 cells, it targets RIPK3 to induce cell necroptosis, and in nasopharyngeal carcinoma, shikonin upregulates both RIPK1 and RIPK3 expression and MLKL expression to promote necroptosis." (PMID 39584140, 2024).
Neonatal sepsis (1 paper, 2022). Systemic inflammatory response to infection in newborn babies. "In a model of cecal slurry-induced neonatal sepsis, mice administrated with Nec-1 or RIPK3 deficiency exhibited resistance against systemic and pulmonary inflammation-mediated lung injury and improved survival." (PMID 36361505, 2022).
neuroblastoma (1 paper, 2021). Neuroblastoma (NB) is the most common solid, extracranial childhood tumor. "Activation of TLR3 triggers the extrinsic apoptotic pathway with Caspase-8 as an apical caspase in the Caspase-8 positive, RIPK3 negative Neuroblastoma cell line, SK-N-AS6." (PMID 34011952, 2021).
neurogenic muscle atrophy (1 paper, 2026). "Targeting RIPK3 preserves muscle mass and may offer a novel therapeutic strategy for neurogenic muscle atrophy, with possible implications for related wasting disorders." (PMID 42063351, 2026).
nevus (1 paper, 2015). Nevus (or naevus, plural nevi or naevi, from nævus, Latin for "birthmark") is the medical term for sharply circumscribed[1] and chronic lesions of the skin or mucosa. "Interestingly, the absence of necroptosis signalling correlated with a lack of receptor-interacting protein kinase-3 (RIPK3) mRNA and protein expression in all cell lines, whereas primary melanocytes and cultured nevus cells strongly expressed RIPK3." (PMID 26355347, 2015). "When compared with HaCaT keratinocytes, primary melanocytes (Mel #20 but not Mel #19) and both cultured nevus cells highly expressed RIPK3 mRNA." (PMID 26355347, 2015).
ocular infection (1 paper, 2022). "Since RIPK3 or MLKL deficient mice are viable, such mice would provide insights into the contribution of RIPK3-MLKL mediated necroptosis to HSV1 ocular infection." (PMID 35464953, 2022).
osteomyelitis (1 paper, 2025). An acute or chronic inflammation of the bone and its structures due to infection with pyogenic bacteria. "Preclinical models have associated PANoptosis with sterile inflammatory conditions, exemplified by the prevention of chronic recurrent multifocal osteomyelitis in mice through the concurrent deficiency of Caspase-1, Caspase-8, and RIPK3—key PANoptosis components." (PMID 40664640, 2025).
ovarian tumors (1 paper, 2014). "This raised the question as to what the relative expression of RIPK3 in ovarian tumors might be." (PMID 25356865, 2014).
overnutrition (1 paper, 2022). An imbalanced nutritional status resulting from excessive intake of nutrients. "After 3 consecutive days of overnutrition, zMIR fish exhibit more severe ER stress in β cells, triggering Ripk3-mediated induction of il1b expression and subsequent macrophage recruitment, β cell loss, and glucose dyshomeostasis." (PMID 36001973, 2022).
periapical periodontitis (1 paper, 2022). Inflammation of the periapical tissue. "Consistently, bone loss was also alleviated in Fusobacterium nucleatum-induced experimental apical periodontitis in mice after inhibition of RIPK3 using an adeno-associated virus." (PMID 35708336, 2022). "In addition, necroptosis was induced in an E. faecalis-infected refractory periapical periodontitis mouse model, in which inhibition of necroptosis by RIPK3 deficiency could markedly alleviate inflammation and bone destruction." (PMID 35708336, 2022). "We investigated whether the RIPK3/MLKL signaling pathway was activated in periapical lesion specimens obtained from patients diagnosed with refractory periapical periodontitis." (PMID 35708336, 2022). "We found that the phosphorylation levels of RIPK3 and MLKL were elevated in periapical lesion specimens of patients with refractory periapical periodontitis." (PMID 35708336, 2022). "Our study revealed that RIPK3/MLKL-mediated macrophage necroptosis contributes to the development of refractory periapical periodontitis and suggests that inhibitors or treatments targeting necroptosis represent a plausible strategy for the management of refractory periapical periodontitis." (PMID 35708336, 2022).
peripheral nerve injury (1 paper, 2022). Injury to a peripheral nerve. "Recently, RIPK3 has been well-studied in the neuropathic pain model caused by peripheral nerve injury." (PMID 35514432, 2022). "Moreover, one research found that RIPK3 inhibition relieved neuropathic pain induced by peripheral nerve injury by decreasing proinflammatory factors' expressions." (PMID 35514432, 2022).
pneumococcal meningitis (1 paper, 2022). An acute purulent infection of the meninges and subarachnoid space caused by Streptococcus pneumoniae, most prevalent in children and adults over the age of 60. "Ripk3 was expressed to higher levels in larvae infected with S. pneumoniae PLY+ as compared to larvae infected with S. pneumoniae PLY− or phosphate-buffered saline (PBS) control-injected larvae as time progressed during the early stages of pneumococcal meningitis at 3, 6 and 9 hpi." (PMID 36543127, 2022). "To further study the role of this necroptosis or necroptosis-like pathway in pneumococcal meningitis, we infected zebrafish larvae with 200 CFUs of wild-type S. pneumoniae D39V in the hindbrain ventricle and treated them with the necroptosis pathway inhibitor GSK′872, which is an RIPK3 inhibitor." (PMID 36543127, 2022).
primary biliary cholangitis (1 paper, 2022). Primary biliary cholangitis (PBC) is a chronic and slowly progressive cholestatic liver disease of autoimmune etiology characterized by injury of the intrahepatic bile ducts that may eventually lead to liver failure. "Activation of RIPK3-dependent necroptosis is the core event in primary biliary cholangitis (PBC) and experimental cholestasis." (PMID 34700031, 2022).
pulmonary arterial hypertension (1 paper, 2025). Pulmonary arterial hypertension (PAH) is a group of diseases characterized by mean pulmonary artery pressure >20 mmHg and elevated pulmonary arterial resistance leading to right heart failure. "RIPK3-mediated necroptosis and its role in the progression of inflammation have also been identified in the pathogenesis of pulmonary arterial hypertension (PAH)." (PMID 40216765, 2025).
pulpitis (1 paper, 2025). Inflammation of the dental pulp. "Bacterial infection in pulpitis may activate necroptosis through the Toll-Like Receptor 4 (TLR4)-RIPK3 pathway, leading to the release of damage-associated molecular patterns (DAMPs) that disrupt immune homeostasis, while mitochondrial dysfunction-induced ROS further aggravates oxidative stress." (PMID 41142308, 2025).
Renal cyst (1 paper, 2022). A fluid filled sac in the kidney. "Moreover, we detected high levels of Ripk3 in protein lysates from those kidneys, indicating an increased propensity to necroptosis during renal cyst formation and tissue degeneration." (PMID 36460631, 2022).
reovirus infection (1 paper, 2023). "Only in a normal fibroblast cell line (VH10), RIPK3 mRNA was detected, but these cells resist reovirus infection." (PMID 36768641, 2023).
selenium deficiency (1 paper, 2023). A nutritional deficiency disease resulting from inadequate selenium levels in the body, which can lead to impaired function of selenoproteins essential for antioxidant defense and thyroid hormone metabolism. "The high level of expression of c-FLIP, MLKL, RIPK1, and RIPK3 indicated that necroptosis also causes lung damage during selenium deficiency." (PMID 37107171, 2023).
serous ovarian tumor (1 paper, 2014). "In fact, more than three-quarters of serous ovarian tumors expressed RIPK3 levels above the mean expression established across all tumors." (PMID 25356865, 2014).
shigellosis (1 paper, 2023). Shigellosis is a bacterial infection leading to dysentery and is caused by Shigella, which are small, ubiquitous Gram-negative bacteria belonging to the enterobacteria family. "Casp1/11/8–/–Ripk3–/– mice, however, are hyper-susceptible to shigellosis, indicating that programmed cell death is a predominant host defense mechanism against Shigella infection." (PMID 36645406, 2023). "All Casp1/11/8–/–Ripk3–/– mice presented with blood in their feces and one of the ten mice also died of shigellosis within 2 days of infection." (PMID 36645406, 2023). "We find that Casp1/11/8–/–Ripk3–/– mice, which lack the pathways to execute pyroptosis, extrinsic apoptosis, and necroptosis, experience severe shigellosis with a 500-fold increase in colonization of the intestinal epithelium relative to B6 WT mice." (PMID 36645406, 2023).
skin infection (1 paper, 2022). An inflammatory process affecting the skin, caused by bacteria, viruses, parasites, or fungi. "We confirmed that the previously published importance of RIPK3 during systemic HSV-1 infection also holds true during skin infection." (PMID 36146839, 2022).
synucleinopathy (1 paper, 2021). A neurodegenerative disease that is characterized by the abnormal accumulation of aggregates of alpha-synuclein protein in neurons, nerve fibers or glial cells. "Further work, particularly in rodent models, will help further refine our understanding of the upstream signaling events that promote RIPK3 activation in astrocytes in the context of synucleinopathy." (PMID 34333522, 2021).
temporal lobe epilepsy (1 paper, 2025). A localization-related (focal) form of epilepsy characterized by recurrent seizures that arise from foci within the temporal lobe, most commonly from its mesial aspect. "KEY POINTS: In the early stage of experimental temporal lobe epilepsy with hippocampal sclerosis (TLE-HS), we observed activation of RIPK1, RIPK3 and MLKL in CA1 astrocytes, along with a reduction in astrocyte density, providing evidence for necroptotic cell death." (PMID 40629542, 2025).
thymic lymphoma (1 paper, 2022). "In line with this, we further demonstrated that LCK‐mediated RIPK3 activation inhibits thymic lymphoma development through the attenuation of ERK activation." (PMID 36161785, 2022). "This study demonstrates that RIPK3 acts as a negative regulator of thymic lymphoma initiation and progression by inhibiting the proliferation of abnormal CD4+CD8+ DP thymocytes." (PMID 36161785, 2022). "Genetic deletion of Ripk3 in mice results in a spontaneously high incidence of thymic lymphoma along with a shortened overall host survival." (PMID 36161785, 2022). "Collectively, these results suggest the possibility that modulation of PP2A activity may regulate RIPK3‐mediated initiation and the development of thymic lymphoma." (PMID 36161785, 2022). "Our data, therefore suggest that for observing the function of RIPK3 on tumor suppression, especially thymic lymphoma, the effects on tumor development are more easily observed in a tumor‐prone genetic background, with a long‐term in vivo model analysis method." (PMID 36161785, 2022).
thymoma (1 paper, 2022). A neoplasm arising from the epithelial cells of the thymus. "Most (77%, 17/22) of the Ripk3−/− mice developed acute T lymphoblastic leukemia (T-ALL) and died within 200 days, while the remaining Ripk3−/− mice developed a mixture of T-ALL/thymoma and died within 250 days." (PMID 35561683, 2022).
triple-negative breast carcinoma (1 paper, 2025). An invasive breast carcinoma which is negative for expression of estrogen receptor (ER), progesterone receptor (PR), and human epidermal growth factor receptor 2 (HER2). "For example, a combination of SHK and Chi-Ag NPs is able to induce effective ICD in triple-negative breast cancer tissues by synergistically inducing tumor cell necroptosis through the upregulation of RIPK3, pRIPK3, and tetrameric MLKL expression." (PMID 40305291, 2025).